BCL2 (BCL2 apoptosis regulator)
Diseases named in the same sentence as BCL2 in open-access papers (continued):
Sharing a sentence is not in itself a finding about the gene and the disease.
melanoma (continued). "All together, those results indicated that the growth inhibitory effects of LNP4 is mediated by the simultaneous inhibition of Bcl-2 and VEGF-A oncogenes in BRAF-mutant melanoma cells." (PMID 32178301, 2020). "In pre-clinical studies, PNT2258 was active in BCL-2 driven xenografts, including in NHL, prostate cancer and melanoma." (PMID 32131385, 2020). "Further study showed that shikonin decreased the levels of STAT3-targeted genes Mcl-1, Bcl-2, MMP-2, vimentin, and Twist, which are involved in melanoma survival, migration, and invasion." (PMID 32536866, 2020). "Our data showed that shikonin inhibited the expression levels of antiapoptotic proteins Bcl-2 and Mcl-1, and enzymatic activities of collagenases MMP-2 and MMP-9, which play vital roles in melanoma metastasis." (PMID 32536866, 2020). "Forced expression of bcl-2 in M14 and A375SM-SC1 melanoma cells resulted in a significant increase of both protein and mRNA levels of COX-2, as well as secretion of PGE2." (PMID 32269145, 2020). "BCL2L10 is a pro-survival factor in melanoma since its expression reduced the cytotoxic effects of cisplatin, dacarbazine, and ABT-737 (a BCL2, Bcl-xL, and Bcl-w inhibitor)." (PMID 33396645, 2020). "FKB treatment (0–10 μg/mL, 24 h) dose-dependently favored the expression of activator Bax with a dramatic decrease in the expression of inhibitor Bcl-2 in A375 and A2058 cells and signified the FKB-mediated apoptosis activation in melanoma cells." (PMID 33053749, 2020). "GAS5 knockdown increases melanoma cell proliferation by inducing Cyclin D1, CDK4, and p27 expression and inhibiting apoptosis via increasing Bcl-2 expression." (PMID 31500396, 2019). "The ABT-263 and A1331852 combination data closely mirrored each other, suggesting that the critical proteins for melanoma cell survival are MCL-1 and BCL-XL, although BCL-2 has some involvement." (PMID 31019203, 2019). "To confirm that key pro-survival proteins targeted by BH3-mimetics (BCL-2, BCL-XL, MCL-1) were expressed in more clinically-relevant patient-derived tissue, we performed immunohistochemistry on 127 biopsies from melanoma patients with Stage III/IV disease." (PMID 31019203, 2019). "Our studies showed that MCL-1 and BCL-XL must be co-targeted to achieve the most effective melanoma cell killing, though co-operativity was also observed by co-targeting MCL-1 and BCL-2." (PMID 31019203, 2019). "The most promising compound was able to stabilize G-quadruplexes that formed in the promoter regions of two target genes relevant to melanoma, KIT and BCL-2." (PMID 31635389, 2019). "Quantification analysis further indicated that the Bax/Bcl-2 ratio and LC3-ΙΙ/LC3-Ι conversion were significantly increased in Ad-POMC-infected melanoma tissues." (PMID 30062060, 2018). "Since melanoma has high levels of Mcl-1 expression, these cells have resistance to ABT-737 (a selective inhibitor of Bcl-2, Bcl-xL, and Bcl-w)-induced apoptosis." (PMID 30463333, 2018). "For melanoma, the levels of MAPK_pT202_Y204, PTEN, and Bcl-2 are decreased, and IGFBP2, E-Cadherin, Akt_pT308, and Akt_pS473 are increased." (PMID 30442178, 2018). "Clinically, primary human melanoma expression microarrays reveals tight linkage between MITF and BCL2." (PMID 30544544, 2018). "In our melanoma model, the expression of these genes is increased in the tumor cell lines and, as hypothesized, there was a significant reduction of Cdkn1a, Bcl2 and Psen2 expression in SIRT1-silenced 4C11+ melanoma cell line (respectively) compared to non-silenced cell lines." (PMID 29383100, 2017).
melanoma (continued). "The results here suggest that the use of a combination of MCL-1 and BCL-2 inhibitors to induce NOXA and BIM is a promising treatment strategy for melanoma regardless of the mutation status of BRAF or NRAS, and it may overcome melanoma's resistance to current treatments." (PMID 27086916, 2017). "We also provide additional results to our previous ones, regarding the role of BCL-2 in tumor invasion, migration, and metastatization by demonstrating BCL-2 ability to promote CSC phenotype in melanoma." (PMID 29238043, 2017). "In summary, BCL-2 was a key regulator of autophagy and cell cycle arrest induced by DHODH inhibition in melanoma cells." (PMID 29348830, 2017). "Our data here suggests that using a combination therapy to inhibit BCL-2 and increase NOXA can be a promising approach to more thoroughly eradicate melanoma." (PMID 27829238, 2016). "As the BAX/BCL-2 ratio seems to be the determinant for setting a threshold for cells undergoing apoptosis, we studied the effect of Lebein on BCL-2 and BAX protein expression to understand its therapeutic potential in melanoma." (PMID 27399772, 2016). "In melanoma, HDAC inhibitors inhibit expression of anti-apoptotic proteins survivin, Bcl-XL, Bcl-2, Mcl-1, XIAP, mostly via decreased transcription." (PMID 26426052, 2015). "OA has been shown to decrease the expression of Bcl-2 and increase the expression of Bax in B16F10 melanoma cells." (PMID 26225949, 2015). "BCL-XL, BCL-2 and ML-IAP were expressed at lower levels in all patient-derived melanoma populations." (PMID 26035829, 2015). "The goal of our recent work was to explore the utility of inhibitors to the anti-apoptotic BCL-2 proteins in lowering the threshold to PLX4032- and GSK1120212-induced apoptosis in melanoma cell lines." (PMID 26501069, 2015). "Taken together these results indicate that effectiveness of combination treatment on melanoma cells is due to an induction of BIM and a simultaneous decrease in expression of anti-apoptotic proteins Bcl-2, Bcl-XL and XIAP." (PMID 26087189, 2015). "Oligonucleotide sequences targeted along the 5′ region upstream of the BCL-2 ATG start site were synthesized and tested for antiproliferative activity against breast and melanoma cell lines." (PMID 24832107, 2014). "A nanoparticle was made to carry Bcl-2 siRNA (as well as Myc and VEGF) for the treatment of melanoma." (PMID 25101298, 2014). "In melanoma, TRD led to expression of the proapoptotic Bax and to inhibition of the antiapoptotic Bcl-2 critical mediators of the intrinsic pathway." (PMID 25568670, 2014). "In particular, the ability of dinaciclib to regulate these anti-apoptotic proteins is likely to be of great utility in melanoma where overexpression of XIAP, Bcl-2 and Mcl-1 is commonplace and can contribute to melanoma chemoresistance." (PMID 23527225, 2013). "Systemic delivery of the U1 adaptors targeting BCL2 and GRM1 suppresses tumor growth in melanoma xenografts by up to 60–70%." (PMID 24285958, 2013). "Several studies have shown that many anti-apoptotic genes and proteins, including Bcl-2 and IAP family members, are expressed at high levels in human and canine malignant tumors, including melanoma and osteosarcoma." (PMID 24260303, 2013). "Recently, in an important proof-of-concept study, the U1 adaptor approach was shown to be highly effective in suppression of melanoma growth in xenografts models, by targeting metabotropic glutamate receptor 1 (GRM1) and B-cell lymphoma 2 (BCL2) transcripts." (PMID 24285958, 2013). "NF-κB target apoptotic protein expression, such as cleaved caspase-3, cleaved PARP, and Bax, was elevated, whereas the survival protein expression levels, such as Bcl-2, C-IAP1, was decreased in the melanoma tissues of CCR5−/− mice." (PMID 22567084, 2012). "Several factors involved in melanoma invasion, resistance to apoptosis and proliferation, such as MMP-2, MCAM/MUC18, BCL-2 and TGF-α are regulated by both CREB and AP-2α, albeit in an opposite manner." (PMID 20805990, 2010).
melanoma (continued). "In melanomas, MITF targets a number of genes with antagonistic behaviors, including genes such as CDK2 and Bcl-2, which promote cell cycle progression and survival, as well as p21CIP1 and p16INK4A, which halt the cell cycle." (PMID 19828018, 2009). "Despite all the evidence suggesting that MITF must be down-regulated for melanoma progression, MITF expression is essential for proliferation and survival of melanoma cells because it regulates genes such as CDK2 and BCL-2 respectively." (PMID 18628967, 2008). "After IL-2 culture in melanoma TIL, high levels of Fas and Bax and low Bcl-2 expression were observed." (PMID 12610520, 2003). "The strong activation of MITF/Bcl‐2 pathway is one of reasons that lead to acquired resistance of MEK inhibitor for NRAS‐mutant melanoma, and anti‐Bcl‐2 (ABT‐199) annihilated the acquired resistance and restored the sensitivity of NRAS‐mutant melanoma cells to MEK inhibitor." (PMID 41492362, 2026). "AE1/AE3, HMB45, BCL2, and pan-melanoma: negative, excluding epithelial, melanocytic, and lymphoid origin." (PMID 40755697, 2025). "Western blot analysis demonstrated increased levels of pro-apoptotic cleaved caspase-3 (c-caspase-3) and epithelial marker E-cadherin, alongside decreased levels of anti-apoptotic Bcl-2 and mesenchymal marker Vimentin, reinforcing the oncogenic function of COL11A2 in melanoma." (PMID 40574832, 2025). "Interestingly, Bcl2A1 was much lower than the canonical Bcl2, which was the opposite of the case in BCG-vaccinated melanoma patients." (PMID 40699791, 2025). "Such levels resulted impaired in Sh FKBP51 RNA but not control cells (Sh Ctrl RNA); exogenous FKBP51 restored BCL-2 expression levels in silenced melanoma cells." (PMID 40180895, 2025). "EBI3 was evidently highly-expressed in melanoma, and silencing of EBI3 could visibly suppress the survival and migration/invasion of melanoma cells, concurrent with the increased levels of BAX and CDH1 and the decreased expressions of BCL2 and CDH2." (PMID 39726752, 2024). "Finally, in order to study the role of cancer-specific Bcl-2 in TME, we showed that melanoma cells overexpressing Bcl-2 were able to stimulate in vitro fibroblasts migration and proliferation." (PMID 38755629, 2024). "Our current study has hinted that EBI3 silencing could suppress the proliferation, migration and invasion of melanoma cells, concurrent with the diminished expression of CDH2 and BCL2 yet the upregulated expression of CDH1 and BAX." (PMID 39726752, 2024). "In addition, studies had shown that apigenin (a flavonoid) exerted antiproliferative activities on human melanoma cell lines A375P and A375SM through the activation of the apoptotic pathway and the decrease of the antiapoptotic protein Bcl-2 expression." (PMID 38371392, 2024). "Detection of MID for rhabdomyosarcoma included myogenins, MyoD1 and PAX-FOXO1 fusion transcript, for synovial sarcoma—Bcl-2 protein and SYT-SSX fusion transcript, for clear cell sarcoma—S100 and melanoma cocktail and EWS-ATF1 fusion transcript by IHC and RT-qPCR." (PMID 37686475, 2023). "After treatment, excessive DNA damage in melanoma cells leads to an increase in the expression of pro‐apoptotic genes (Caspase‐3) and a decrease in the expression of DNA repair gene (PARP1) and anti‐apoptotic gene (Bcl‐2) to activate the apoptosis pathway." (PMID 36241419, 2023). "ZBSO treatment resulted in an increase in the Bax/Bcl-2 ratio from 1.03 to 2.89 (p < 0.05), which suggests that ZBSO may promote apoptosis in human melanoma A375 cells." (PMID 37081962, 2023).
melanoma (continued). "However, POMC overexpression reduces the melanoma growth by apoptosis and autophagy via complex α-MSH-HIF-1 α/BCL2 and adenovirus E1B 19-kDa-interacting protein 3 (BNIP3) signalling pathways." (PMID 35334544, 2022). "LHFPL3-AS1 upregulates the miR-181a-5p/BCL2 and miR585/STAT3 feedback loops, which are required for melanoma migration, invasion, and growth in vitro and in vivo and is an unfavorable prognostic marker in melanoma patients." (PMID 35159386, 2022). "Moreover, inhibition of TUG1 expression can downregulate Bcl-2, MMP-9 and cyclin D1 protein, reduce the growth of tumors in melanoma and improve the chemosensitivity of A375 cells to cisplatin and 5-FU." (PMID 36601121, 2022). "Concordantly with the gene modulation results, a significant reduction in miR-214-3p, targeting BAX, and a significant up-regulation of miR-16-5p, targeting BCL2 and BIRC5, and of miR-193a-3p, targeting MCL-1, were observed in PEL and EPI -treated melanoma cells." (PMID 35877720, 2022). "In a separate study, CRISPR/Cas9 mediated knockout of BFL-1 in melanoma cells were not sensitized to pharmacological inhibition of MCL-1, BCL-XL, and BCL-2 indicating that the melanoma cells do not rely on BFL-1 for survival." (PMID 35201512, 2022). "In the human melanoma A375 cell line, EGCG inhibited growth through the activation of the apoptotic pathway, with an increase in the pro-apoptotic protein caspase 3 and with a decrease in the anti-apoptotic protein BCl-2." (PMID 35877341, 2022). "By stimulating melanoma cells with IL-10 (20 ng/mL), it was found that the expression of AMPK was significantly decreased in A375 and H1205-lu cells, while the expression of BCL-2 was also significantly increased in H1205-lu cells." (PMID 35893303, 2022). "Another small molecule inhibiting Bcl-2, Bcl-xL and Bcl-w is represented by ABT-737, whose effect on melanoma was demonstrated because of its ability to empower the efficacy of several therapeutic strategies including immunotoxins and BRAF or MEK inhibitor in BRAF-mutated cells." (PMID 33803452, 2021). "Additionally, oncogenes that can be regulated by epigenetic modifiers and support melanoma progression and development include RAS, ERK, c-jun, MITF, MDM2, and BCL-2." (PMID 34944799, 2021). "In human melanoma cells, EGF treatment can promote STAT5 activation via tyrosine-protein kinase Src (Src) and Janus kinase 1 (JAK1) signaling leading to STAT5 nuclear translocation along with upregulation of the STAT5 target, Bcl-2, an antiapoptosis protein." (PMID 34067095, 2021). "Consequently, IL-1β-stimulated MAFs enhance the survival of MAPKi-treated melanoma cells in an ERK-independent manner, via NF-κB activation and bcl2 upregulation." (PMID 34067929, 2021). "The dual BCL-XL/BCL-2 inhibitor Navitoclax was also shown to synergise with BETi in small cell lung cancer, colorectal cancer, glioma and B-cell lymphomas, whilst BH3-mimetics targeting MCL-1 enhance BETi activity in AML and melanoma." (PMID 33799592, 2021). "A different involvement of Bcl-xL and Bcl-2 was also reported in the study of Zhang and Rosdahl, indicating that Bcl-xL, but not Bcl-2, was a key protein in the induction of apoptosis after ultraviolet-B exposure in melanoma cells." (PMID 33803452, 2021). "Also, CUR activates apoptosis pathways in B16-F10 melanoma cells more than in L929 normal cells by increasing the expression of CASP3 and decreasing BCL2 expression." (PMID 34825002, 2021). "Thus the potentiation of apoptosis induced by co-inhibition of BCL2 and MCL1 is a strategy with wide applicability to enhance the anti-melanoma activity by targeted therapies in malignant melanoma." (PMID 34331013, 2021). "This led us to hypothesize that inhibition of family members other than BCL2, in combination with AZA treatment, may be more potent in melanoma." (PMID 34451846, 2021).
melanoma (continued). "Toxicity data for MCL1 and BCL2 inhibition in humans has not been reported to date, however, early phase clinical trials assessing safety are underway in non-melanoma tumor types." (PMID 32764384, 2020). "As chemotherapy primarily eliminates cancer cells by apoptosis, we here evaluated if the expression of key apoptosis regulators (Bax, Bak, Bcl-2, Bcl-xL, Smac, Procaspase-9, Apaf-1, Procaspase-3 and XIAP) allows prognosticating PFS in stage III/IV melanoma patients." (PMID 32054850, 2020). "Moreover, there was a significant increase in the expression of apoptosis marker, cleaved Caspase-3, in melanoma cells upon UNC0642 treatment according to Western blot analysis, while the expression of Bcl-2 was remarkably reduced." (PMID 32015216, 2020). "Boswellia carterii EO (frankincense oil) was found to induce apoptosis through downregulation of Bcl-2 and up regulation of Bax proteins in B16-F10 cells, while inducing down regulation of Mcl-1 and cleavage of caspase 3 and 9 and PARP in human melanoma FM94 cells." (PMID 32948083, 2020). "The results showed that the Bcl-2 silencing significantly promoted apoptosis of melanoma stem cells compared with the control, indicating that Bcl-2 played a negative role in apoptosis of melanoma stem cells." (PMID 33149126, 2020). "Despite high expression of BCL2 in melanoma compared to other lineages, the response to AZD4320 was not replicated by selective BCL2 inhibition with venetoclax, but rather was recapitulated using the selective BCL-XL inhibitor A-1155463." (PMID 31727888, 2019). "Notably, many BCL-2 proteins are downstream factors of the RAS/BRAF/MAPK and PI3K/AKT signaling pathways, the activation of which contributes to the relapse of melanoma from treatment with targeted therapies." (PMID 31635389, 2019). "The expression of miR‐365 is lower in melanoma cells than in normal melanocytes, and it was observed that overexpression of miR‐365 inhibits proliferation and induces cell cycle arrest via inhibition of its targets, CCND1 and BCL2." (PMID 30499222, 2019). "BCL2 inhibition may, however, slightly enhance the effect of BCL-XL inhibition when the ERK1/2 pathway is inhibited in some melanoma cells." (PMID 31727888, 2019). "Our data show for the first time that therapies targeting specific combinations of BCL-2 pro-survival proteins, namely MCL-1 plus BCL-XL and MCL-1 plus BCL-2, could have significant benefit for the treatment of melanoma." (PMID 31019203, 2019). "Lack of G6PD in mice melanoma cells enhances apoptosis by upregulating Fas and downregulating Bcl-2 and Bcl-xL." (PMID 31500396, 2019). "Of note, although GCNT2 KD melanoma cells plated on plastic did show a slight increase in expression of prosurvival genes BCL-2 and BCL-XL, upon engagement with ECM, GCNT2 KD melanoma cells significantly upregulated the expression of both BCL-2 and BCL-XL." (PMID 30135430, 2018). "In addition, the expression of cleaved PARP and Bax increased after VB1 treatment, whereas that of BCL2 decreased, which indicates that VB1 induces melanoma cell apoptosis." (PMID 30400954, 2018). "Our results, which indicate that GLSE treatment mediates an increase in Bax expression and a corresponding down-regulation of Bcl-2, suggest that this may be a possible route through which GLSE induces apoptosis in non-melanoma skin cancer cells." (PMID 29914183, 2018). "In addition, GCNT2/I-branched glycan expressing melanoma cells displayed higher levels of proapoptotic genes, BID and BAX, and had lower expression of prosurvival genes, BCL-2 and BCL-XL." (PMID 30135430, 2018). "In this paper, we evidence Sema5A expression in metastatic specimens from melanoma patients, and we show that Sema5A expression modulates in vitro melanoma cell migration and invasion, activates the Akt/ERK pathway and is regulated by Bcl-2 and the miR-204/c-Myb axis." (PMID 30454024, 2018).